TNF (tumor necrosis factor)
Diseases named in the same sentence as TNF in open-access papers (continued):
Sharing a sentence is not in itself a finding about the gene and the disease.
metabolic disorders (continued). "Activated MAIT cells exhibit T helper 1 (Th1)/Th17 secretion patterns, such as interferon gamma (IFNγ), tumor necrosis factor alpha (TNF-α), and IL-17, and may be involved in the pathogenesis of various inflammatory diseases and metabolic diseases." (PMID 36499635, 2022). "In addition, other bioactive factors, such as leptin, adiponectin, tumor necrosis factor-α, interleukin-6, interleukin-8, and MCP-1, can also be released from perirenal fat, which is involved in the pathogenesis of CVD, metabolic disorders, and T2DM." (PMID 35370949, 2022). "Research has indicated that Artemisia plant extracts could prevent metabolic disorders induced by a high-fat diet in mice by downregulating the expression of CD36, TNF-α, IL-6, IFN-α and IFN-β genes in epididymal adipose tissue." (PMID 35625074, 2022). "Overall, the mechanisms explaining the relationship between TNF-α, body weight changes, and metabolic disorders are not yet clear." (PMID 36010524, 2022). "Moreover, supplementation with 25(OH)D can improve metabolic disorders and alleviate inflammatory response of T2DM patients via reducing a number of inflammatory factors such as IL-6, CRP, and TNF-α levels." (PMID 36619542, 2022). "Adipocytes not only produce TNFα; they also express both receptors (TNFR1 and TNFR2), and respond to TNFα in a feedforward cycle that contributes to adipose tissue dysfunction during metabolic disease." (PMID 33669239, 2021). "TNF is one of the key genes of the T2DM pathway, is a key proinflammatory adipocytokine that is released from adipocytes and adipose tissue-derived mesenchymal stem cells, especially in subjects afflicted with certain metabolic diseases." (PMID 34740995, 2021). "Given the disease-related changes in levels of relevant cytokines (for instance, leptin, adiponectin, reisitin, FGF21, Fetuin A, TNF-α, IL-6, MCP-1), these factors may serve as biomarkers for the early detection of metabolic disorders." (PMID 31736870, 2019). "Four plant derivatives, perillaldehyde, wogonoside, cinnamaldehyde, and 6-shogaol reduced levels of TNFα without decreasing IL-10, marking these compounds as potential immunomodulatory therapeutics for metabolic disease." (PMID 30944419, 2019). "Taken together, our study demonstrated that PMQ up-regulates adiponectin expression via a mechanism that implicates PPARγ together with TNF-α and IL-6, suggesting that PMQ might be a potential candidate for the treatment of metabolic diseases." (PMID 21734632, 2011). "Embryotoxic cytokines, such as tumor necrosis factor (TNF), TNF-related apoptosis-inducing ligand (TRAIL), and interferon-gamma (IFN-γ), could participate in the programming of fetal growth restriction or development of metabolic disorders." (PMID 38612572, 2024). "Intercellular adhesion molecule-1 (ICAM-1), monocyte chemoattractant protein-1 (MCP-1), tumor necrosis factor-α (TNF-α), and plasminogen activator inhibitor-1 (PAI-1) are potent biological markers for the development of inflammatory and metabolic diseases which may include PCOS." (PMID 36793022, 2023). "In metabolic disorder like T2DM, the adipose-resident macrophages are polarized towards a pro-inflammatory (M1-polarized) phenotype, increasing the expression of inflammatory mediators, including interleukin-6 (IL-6), tumor necrosis factor-α (TNF-α), and IL-1β." (PMID 35173531, 2022). "In this study, Met-Met significantly suppressed LPS-induced TNF-α, IL-8, AP-1, and MCP-1 expression; reversed decreased tryptophan, phenylalanine, and histidine levels; and inhibited LPS-induced palmitic acid and stearic acid levels as well as purine metabolism disorder." (PMID 33809487, 2021). "Hence, this endocrine disruptor may be responsible for the development of metabolic disorders, promoting in fat cells an increase in proinflammatory pathways and upregulating the expression and release of certain cytokines, such as IL6, IL1β, and TNFα." (PMID 37175934, 2023).
metabolic disorders (continued). "In addition, a meta-analysis focusing specifically on HIT reported improvements in tumor necrosis factor-alpha (TNF-α), leptin, and adiponectin levels among individuals with metabolic disorders, though no significant changes were observed in CRP levels." (PMID 41590696, 2026).
immune dysfunction (265 papers, 2002 to 2026). "It is well established that the pro-inflammatory cytokine TNF-α is highly expressed in rheumatoid joints, causing immune disorders and promoting RA pathogenesis." (PMID 40147153, 2025). "IBS-D-associated intestinal mucosal immune dysfunction disrupts both motility and barrier function, with TNF-α, IL-6, and MFGE8 serving as key mediators linking inflammatory signaling, apoptosis regulation, and barrier repair pathways." (PMID 40895313, 2025). "B cells in RA synovium induce the production of cytokines such as IL-1α, IL-23, IL-12, IL-6, and TNF-α, causing bone damage, inflammation, and immune disorders." (PMID 39139563, 2024). "Studies have shown that immune disorders in RA patients are mainly caused by the activation of specific signaling pathways by IL-6, IL-l, TNF-α, and other cytokines." (PMID 35784680, 2022). "Regarding patients who have immune system diseases, treatments with steroid hormones, biological response regulators, and antitumor necrosis factor-α (TNF-α) are closely linked to the reactivation of TB." (PMID 36288019, 2022). "Local synthesizing process for cytokine (e.g., IL-1α, IL-23, IL-12, IL-6, and TNF-α) under the induction from local autoreactive B cell was suggested to impact pathology-associated RA cells, triggering bone injury, inflammation, and immune disorder." (PMID 34691030, 2021). "The activation of pro-inflammatory cytokines, such as TNF-α, IL-1β, and IL-6, in intestinal inflammatory cells can cause a cascade of intestinal inflammation that leads to local inflammation and immune system disorders." (PMID 34348563, 2021). "In the process of transforming MPP into RMPP, the monocytes and macrophages secreted large amounts of TNF-α, triggering a series of inflammatory reactions, immune disorders, thereby causing damage to organs." (PMID 34177587, 2021). "INF-γ, IL-12, TNF-α, and IL-6 are all pro-inflammatory cytokines which can cause immune disorders and amplify the inflammation." (PMID 28587089, 2017). "If SCD effectively mitigates TNF-α-driven inflammatory damage, it could improve survival rates by preventing the cascade of immune dysfunction associated with ECMO-related complications." (PMID 41010904, 2025). "Additionally, their work highlighted the role of genetic mutations and dysregulation in inducing immune dysfunction, resulting in TNF-α mutations." (PMID 38474052, 2024). "The cited study revealed inflammation of the small intestine in pregnant sows as well as changes in newborn piglets where immune dysfunctions and increased expression of the genes encoding proinflammatory cytokines IL-6, IL-1α, IL-1β, and TNFα were observed in the small intestine." (PMID 32471145, 2020). "Therefore, we screened pro-inflammatory cytokines IL-1β, TNF-α, and IL-6, which cause immune disorders and amplify inflammation, as well as anti-inflammatory cytokine IL-10." (PMID 31500342, 2019). "Among indications of immune dysfunction associated with increased exposures to PCBs and dioxins, mononuclear cells from cord blood showed decreased in vitro secretion of tumor necrosis factor-α after mitogenic stimulation; this cytokine is an important proinflammatory stimulant." (PMID 20562055, 2010). "In addition, it has recently been demonstrated that mortality in HIV and M. tuberculosis co-infected patients is linked to immune dysfunction of monocytes, especially related to inflammatory mediator production of IL-6, TNFα, and CSF3 and expansion of CD16+CD14+ monocytes." (PMID 29770360, 2018). "From our data, K88 significantly upregulated proinflammatory cytokine expression (e.g., IL-1β, TNF-α, IFN-γ) in the ileum, which possibly caused immune disorders in the ileum, exacerbated inflammation, and damaged ileum tissue." (PMID 39857392, 2025). "Abnormally high baseline values of IFN-γ, IL-6, and TNF-α were observed in one patient at DL 400 mg who experienced treatment-emergent grade 3 nausea and grade 4 immune system disorder (hypersensitivity)." (PMID 40875525, 2025).
immune dysfunction (continued). "Age-related immune dysfunction (including reduced T-cell activity,impaired antibody production, and elevated cytokines such as IL-6 and TNF-α) isassociated with severe outcomes, such as cytokine storms and multi-organ failure." (PMID 41337512, 2025). "Studies have shown that excessive alcohol intake increases pro-inflammatory cytokines, such as TNF-α and IL-6, contributing to chronic inflammation and immune dysfunction." (PMID 39846539, 2025). "Overexpression of IL-1β and TNF-α can lead to immune dysfunction in the body, resulting in host inflammation." (PMID 40342298, 2025). "The significant inhibition of M. comosus extracts against IL-1β, TNF-α and IL-6 makes it a potential therapeutic target against multiple immune disorders." (PMID 38310564, 2024). "Purpurin played an anti-inflammatory role by inhibiting IL-6, TNF-α, and IL-1β and increasing IL-10, and regulated immune disorder by decreasing the CD4+/CD8+ ratio and increasing the FOXP3 level." (PMID 36615560, 2023). "Increased levels of proinflammatory mediators from M1-type macrophages lead to inflammation and immune disorders, such as TNF-α, IL-6, and IL-1β." (PMID 37035757, 2023). "On the other hand, during the active phase of CHB, immune system disorders aggravated liver cell necrosis, increasing tumor necrosis factor, endotoxin, and various cytokines (such as interleukin-1 and interleukin-6)." (PMID 35402467, 2022). "The colocalization of several TNF receptor superfamily members (TNFRSF1A, TNFRSF9, and TNFRSF14) further supports the development of drugs modulating TNF pathway, one of the main therapy lines for treating immune diseases." (PMID 35591976, 2022). "TNF-α is essential to inflammation regulation, especially inflammatory cytokine production; the impairment of TNF-α synthesis has long been suggested as relevant for immune disorders and complex diseases pathogenesis." (PMID 36339838, 2022). "Through the KEGG pathway analysis, we found DEGs mainly enriched in immune system diseases and immune-related pathways, such as TB, IL-17 signaling pathways, NF-kappa B signaling pathway, and TNF signaling pathway." (PMID 35463752, 2022). "It is well known that macrophages and T cells produce large amounts of IL-23 and TNF-α in immune disorders, such as CD, and are considered to play a central role in the pathophysiology of CD." (PMID 35809093, 2022). "TNF-α is one of the most important pro-inflammatorycytokines and plays a critical part in immune disorder pathogenesis." (PMID 32840387, 2021). "Chronic stress also promotes the development of tumors by causing immune disorders in the body, which decrease the numbers of CD4+ and CD8+ cells around tumors and reduce tumor necrosis factor, interferon and macrophage levels." (PMID 34988010, 2021). "B. breve CCFM1026 significantly reduced the proportion of neutrophils and increased lymphocytes, the expressions of TLR7, MyD88, TRAF6, and TNF-α to restore the immune disorders." (PMID 33924002, 2021). "Understanding of the TNF-α signaling mechanism has been expanded and applied for the treatment of immune diseases, which has resulted in the development of effective therapeutic tools, including TNF-α inhibitors." (PMID 33800290, 2021). "Proinflammatory cytokines TNF-α and IL-6 have been reported to result in mucosal inflammation and aggravate immune disorders." (PMID 34195297, 2021). "The human TNF receptor fusion protein etanercept (Enbrel®), which can neutralize TNF, has been used to treat auto-immune diseases in the clinics." (PMID 31645676, 2020). "As one of the main controllers of the immune response, many pro-inflammatory cytokines such as IL-6, IL-1β, and TNF-α have been reported to respond to stress and immune disorders, and IL-6-related pathways also play a key role in regulating acute heat stress." (PMID 33233727, 2020).
immune dysfunction (continued). "Introduction of CARDS toxin caused damage to mouse lung tissues, accompanied by the increase of the expression of the pro-inflammatory cytokines (such as TNF-α and IL-6) and immune disorders." (PMID 31399022, 2019). "TNF-α is an inflammatory cytokine, which actively participates to the maintenance of chronic and auto-immune disease." (PMID 31212848, 2019). "The imbalance of proinflammatory cytokines, such as IL-6, TNF-α, IL-1β, and IL-10, was demonstrated that contributed to immune dysfunction and also mediated inflammation of the tissues and organ damage in SLE." (PMID 31886314, 2019). "Our study shows that CD8+ T cells, CD4+ T effectors, and CD4+ Tregs all contribute to an increase in TNF-α in psoriatic skin, suggesting multiple elements of immune dysfunction." (PMID 30054515, 2018). "CD is characterized as a Th1-mediated inflammatory response with overproduction of interferon-γ (IFN-γ) and TNF-α whereas UC is considered a Th2-mediated immune disease with massive production of interleukin IL-4, IL-5, IL-9, and IL-13." (PMID 30150894, 2018). "Our previous study has indicated that NS post-HSCT is an immune disorder involving immune complex deposition, B cell, Tregs, and Th1 cytokines such as tumor necrosis factor-α (TNF-α) and interferon-γ (IFN-γ)." (PMID 28855905, 2017). "In our series, patients with higher monocyte IL-6 and TNF-α production after re-exposure to LPS had higher 28-day mortality rates and immune dysfunction score." (PMID 29073262, 2017). "Patients with a higher immune dysfunction score also had higher IL-6 and TNF-α elevation ratios after LPS stimulation." (PMID 29073262, 2017). "TNF-α is a major proinflammatory cytokines, its abnormal expression is closely related to the immune dysfunction." (PMID 28824631, 2017). "TNF-α is an important mediator of progression of many immune diseases, due to its strong pro-inflammatory and immunostimulatory activities." (PMID 26978739, 2016). "Recently, a number of biologic agents targeting inflammatory cytokines, such as IL-6, IL-1β and TNF-α have been developed and used as therapeutics for RA and other immune disorders." (PMID 27070121, 2016). "Potent immune modulatory therapeutics like TNFα inhibitors, show potent inhibition of immune diseases, such as rheumatoid arthiritis but their efficacy can be lost over time requiring a second line of therapy." (PMID 26620767, 2015). "The technique of TNF blockade by monoclonal antibodies has been developed as an effective therapy for immune diseases including IBD." (PMID 23484133, 2013). "In this case report, our patient received during one and a half year anti-TNFα concomitant with prednisone because of its immune disease." (PMID 25379301, 2013). "TNF-α is a pleiotropic cytokine involved in the pathogenesis of several immune disorders and hematological malignancies, including AML; a high serum TNF-α level is an adverse prognostic factor for survival in AML." (PMID 24213464, 2012). "Using standard immunization protocols, we were able to induce strong antibody responses in this strain against highly conserved human antigen MIF or mouse self-antigen TNF-alpha before the onset of auto-immune disease." (PMID 19564921, 2009). "Specifically, studies have shown that the activation of 5-HT1A and 5-HT2A serotonin receptors suppresses the production of interferon-gamma (IFN-γ) and TNF-α, weakening the cellular immune response and promoting the development of immune dysfunction under chronic stress." (PMID 39857306, 2025). "Additionally, L. plantarum K55-5 has exhibited potential for immune induction in immunosuppressed mouse models, with its LTA leading to high TNF-α levels, suggesting its potential use in treating immune disorders." (PMID 39210803, 2025). "Because CKs are usually regulated in a cascade fashion, there are some studies that may provide only partial insights into SCZ immune dysfunction using TNF-α alone." (PMID 39126046, 2024).